HTT (huntingtin)
Diseases named in the same sentence as HTT in open-access papers (continued):
Sharing a sentence is not in itself a finding about the gene and the disease.
Huntington disease (continued). "Yeast models for characterization of Huntingtin (Htt), the protein that is mutated in patients of Huntington’s disease, were established by testing variants of exon 1 of the N-terminus of human Huntingtin." (PMID 30083092, 2018). "Huntington’s disease (HD) is caused by a CAG repeat trinucleotide expansion within the first exon of the huntingtin gene, and it causes a range of symptoms including motor, cognitive and psychiatric disturbances." (PMID 29445514, 2018). "Huntington's disease is an autosomal‐dominant disease that is caused by an expansion of CAG trinucleotide repeats located in the exon 1 region of the huntingtin gene." (PMID 29972883, 2018). "Huntington’s disease is a progressive neurodegenerative disorder caused by polyglutamine-expanded mutant huntingtin (mHTT)." (PMID 30266909, 2018). "Huntington disease (HD) is a fatal neurodegenerative disorder caused by a CAG expansion in the huntingtin (HTT) gene, leading to selective and progressive neuronal death predominantly in the striatum." (PMID 29945611, 2018). "Huntington’s disease (HD) is a progressive neurodegenerative disease caused by a polyglutamine expansion in the human HTT gene, which is located on chromosome 4." (PMID 30513753, 2018). "For example, the accumulation of misfolded protein such as β-amyloid, α-synuclein, and huntingtin is apparently associated with selective nerve cell death in Alzheimer’s, Parkinson’s, and Huntington’s diseases." (PMID 30241539, 2018). "Huntington's disease (HD) is a neurodegenerative disorder caused by a mutation in the huntingtin gene." (PMID 30460101, 2018). "Here we use natural variation between strains of budding yeast to genetically map loci that influence the aggregation of a polyglutamine-containing protein derived from a mutant form of huntingtin, the causative agent in Huntington disease." (PMID 30194090, 2018). "Huntington’s disease (HD) is an autosomal dominant neurodegenerative disorder that is caused by a CAG repeat expansion in the HTT gene." (PMID 30455625, 2018). "Neuroinflammation, depression and the aberrant activation of C6 are hallmarks of Huntington disease (HD), a progressive neurodegenerative disorder caused by a mutation in the huntingtin gene." (PMID 29560279, 2018). "Huntington disease (HD) is caused by the expression of mutant huntingtin (mHTT) bearing a polyglutamine expansion." (PMID 29510748, 2018). "Huntington's disease (HD) is a progressive autosomal dominant neurodegenerative disorder caused by the expansion of CAG repeats in the first exon of the huntingtin gene (HTT)." (PMID 29535594, 2018). "As such, iPSCs suppress the aggregation of polyQ-expanded huntingtin (HTT), the mutant protein underlying Huntington’s disease (HD)." (PMID 30038412, 2018). "Huntington’s disease is caused by a mutation of the huntingtin gene, resulting in an abnormal huntingtin protein (HTT) with a long polyglutamine, poly(Q) tail in the N-terminal region." (PMID 29910712, 2018). "Huntington disease (HD) is an autosomal dominant neurodegenerative disorder that is caused by an expansion of a polyglutamine tract in the huntingtin (HTT) protein." (PMID 29510748, 2018). "Huntington disease (HD) is an autosomal dominant neurodegenerative disorder caused by a mutation in the huntingtin (HTT) gene which results in progressive neurodegeneration in the striatum, cortex, and eventually most brain areas." (PMID 29643462, 2018). "Huntington disease (HD) is a dominantly inherited neurodegenerative disorder that is caused by an unstable expansion of a CAG repeat within the coding region of the huntingtin (HTT) gene." (PMID 29415038, 2018). "Huntington’s disease is caused by an autosomal dominant mutation in the gene encoding a protein called huntingtin." (PMID 30008670, 2018). "Huntington’s disease (HD) is a hereditary NDD caused by elongated CAG repeats in the Huntingtin (Htt) gene that lead to progressive increases in choreic movements and to neuropsychiatric dysfunction." (PMID 30509290, 2018).
Huntington disease (continued). "Huntington’s disease (HD) is a fatal neurodegenerative disorder caused by an expanded polyglutamine (polyQ) stretch at the amino (N)-terminal of the huntingtin protein (HTT)." (PMID 30310861, 2018). "Huntington's disease is a fatal neurodegenerative disorder resulting from a CAG repeat expansion in the first exon of the gene encoding the Huntingtin protein (Htt)." (PMID 30185623, 2018). "Huntington’s disease (HD) is an inherited neurodegenerative disorder caused by the abnormal expansion of CAG repeats in the huntingtin (HTT) gene, which leads to progressive loss of neurons starting in the striatum and cortex." (PMID 30618623, 2018). "Huntington’s disease (HD) is an autosomal dominant neurodegenerative disorder caused by pathogenic poly-glutamine expansions in the huntingtin gene (HTT)." (PMID 29509900, 2018). "Huntington disease (HD) is a devastating neurodegenerative disorder caused by a CAG repeat expansion in exon 1 of the huntingtin (HTT) gene." (PMID 29945611, 2018). "Huntington's disease (HD) is a hereditary, progressive, neurodegenerative disorder caused by a mutation in the Huntingtin gene (IT15 gene, located on the short arm of chromosome 4), which codes for the protein Huntingtin." (PMID 30028085, 2018). "Huntington’s disease (HD) is an autosomal dominant neurodegenerative disorder caused by an increase in CAG trinucleotide repeats in the huntingtin (HTT) gene, giving rise to an expanded polyglutamine (polyQ) domain in the N-terminal of the encoded HTT protein." (PMID 30618623, 2018). "Huntington disease (HD) is a dominantly inherited neurodegenerative disorder caused by an expanded CAG trinucleotide repeat in the huntingtin (HTT) gene." (PMID 29802276, 2018). "Huntington’s disease (HD) is an incurable neurodegenerative disease, caused by a polyglutamine (polyQ) tract expansion in the huntingtin (HTT) protein." (PMID 29754822, 2018). "The neurodegenerative Huntington’s disease (HD) is caused by a polyglutamine (polyQ) amplification in the huntingtin protein (HTT)." (PMID 30310861, 2018). "Huntington’s disease (HD) is a neurodegenerative disorder caused by an expansion mutation of the cytosine–adenine–guanine (CAG) trinucleotide in the HTT gene." (PMID 29651271, 2018). "Huntington’s Disease (HD) is a neurodegenerative disorder caused by a CAG expansion in the exon-1 of the IT15 gene encoding the protein Huntingtin." (PMID 30450032, 2018). "Huntington’s disease (HD) is a dominantly inherited neurodegenerative disorder caused by a CAG trinucleotide expansion in HTT, which encodes huntingtin." (PMID 29750799, 2018). "Huntington disease (HD) is an autosomal dominant neurodegenerative disorder caused by a mutation in the huntingtin (HTT) gene, which results in brain neurodegeneration and peripheral pathology affecting different organs including testis." (PMID 29883458, 2018). "The CAG repeat expansion that elongates the polyglutamine tract in huntingtin is the root genetic cause of Huntington’s disease (HD), a debilitating neurodegenerative disorder." (PMID 29858077, 2018). "Expansion of polyglutamine stretch in the huntingtin (HTT) protein is a major cause of Huntington's disease (HD)." (PMID 28288000, 2017). "To test this, we asked if Trim-Away can be used to selectively degrade the disease-causing variant of the protein huntingtin, which causes Huntington’s disease." (PMID 29153837, 2017). "Huntington disease is associated with elongation of a CAG repeat in the HTT gene that results in a mutant huntingtin protein." (PMID 28570578, 2017). "The HAP1 protein interacts with the huntingtin protein, which is associated with Huntington disease." (PMID 28750619, 2017). "Huntington’s disease is caused by a polyglutamine expansion mutation in the gene encoding the Huntingtin protein; the mutant protein with a polyglutamine tract accumulates inside neurons as toxic protein inclusions." (PMID 28737703, 2017).
Huntington disease (continued). "Huntington's disease (HD) is an autosomal dominant neurodegenerative disorder caused by a CAG trinucleotide repeat expansion in the huntingtin gene that generates long polyglutamine stretches in the encoded huntingtin protein (HTT)." (PMID 28293168, 2017). "Huntington’s Disease (HD) is a neurodegenerative disorder caused by an expansion in a CAG-tri-nucleotide repeat that introduces a poly-glutamine stretch into the huntingtin protein (mHTT)." (PMID 28920088, 2017). "The cause of Huntington′s disease (HD), an autosomal dominant inherited invariably fatal disorder, is an expansion of a stretch of the huntingtin (HTT) protein." (PMID 28378063, 2017). "Huntington disease (HD) is an autosomal dominantly inherited neurodegenerative disorder, which is caused by a specific mutation in the gene for the huntingtin protein." (PMID 28273120, 2017). "Huntington’s disease (HD) is an autosomal dominant neurodegenerative disorder caused by a glutamine-encoding CAG expansion near the 5’ end of the HTT gene." (PMID 28453524, 2017). "For example, Huntington’s disease is caused by a pQ extension in the Huntingtin (HTT) gene, while spinocerebellar ataxia (SCA) is caused by a similar pQ extension in various genes including Ataxins (e.g., ATXN1-3)." (PMID 28737703, 2017). "The most well studied polyQ expanded gene is HTT, which upon expansion of the homopeptide region, is responsible for the pathogenesis associated with Huntington’s disease." (PMID 29186753, 2017). "This suggests that the impaired Nrf2 activity evident in human Huntington’s disease and genetic models is dependent on the presence of mutated huntingtin." (PMID 28820437, 2017). "Huntington's disease is caused by a polyglutamine stretch expansion in the first exon of huntingtin." (PMID 28537272, 2017). "Our unbiased screen for compounds that protect cells against a pathogenic huntingtin fragment reveal PIP4Kγ as a potential target for Huntington disease." (PMID 29256861, 2017). "Although Nrf2 signalling is impaired in the presence of mutated huntingtin, pharmacological activators of Nrf2 are protective in animal models of Huntington’s disease." (PMID 28820437, 2017). "Several studies have implicated N-terminal huntingtin protein fragments in Huntington disease pathogenesis." (PMID 28570578, 2017). "Huntington disease is a fatal neurodegenerative disorder caused by a CAG repeat expansion in the gene encoding the huntingtin protein." (PMID 29203806, 2017). "Huntington disease (HD) is a genetic disorder caused by propagation of a glutamine (CAG) stretch within the N-terminal part of the huntingtin protein (Htt)." (PMID 28840063, 2017). "Huntington’s disease (HD), caused by expansion of a polyglutamine tract within HUNTINGTIN (HTT) protein, is an autosomal dominant neurodegenerative disease associated with a progressive neurodegeneration of striatum and cerebral cortex." (PMID 29258536, 2017). "Polyglutamine expansion in the huntingtin protein is the primary genetic cause of Huntington's disease (HD)." (PMID 28537272, 2017). "Huntington’s disease (HD) is an autosomal dominant neurodegenerative disorder caused by an extended (≥36) CAG repeat in the Huntingtin (HTT) gene, which varies in length between individuals." (PMID 29016656, 2017). "Huntington’s disease (HD) is a neurodegenerative disorder caused by a CAG trinucleotide repeat expansion in the huntingtin gene." (PMID 28406926, 2017). "The HTT gene coding for Huntington protein, is mutated in Huntington’s disease but is ubiquitously expressed, and mutant HTT also influences cancer progression." (PMID 28054945, 2017). "At the molecular level Huntington’s disease is caused by a CAG repeat expansion within the huntingtin gene encoding for an elongated poly-glutamine (polyQ) tract in the huntingtin protein." (PMID 28680391, 2017). "Huntington’s disease (HD) is a fatal progressive neurodegenerative disorder caused by a mutation in the huntingtin (HTT) gene." (PMID 28771234, 2017).
Huntington disease (continued). "Huntington’s disease (HD) is a progressive, monogenic dominant neurodegenerative disorder caused by repeat expansion mutation in the huntingtin gene." (PMID 28194132, 2017). "Huntington's Disease (HD) is an autosomal dominant neurodegenerative disorder caused by an expanded polyglutamine repeat (polyQ) in one allele of the Huntingtin (HTT) gene." (PMID 29066943, 2017). "Huntington’s disease is a neurodegenerative disease caused by an unstable expanded CAG repeats (>35–39 repeats) in the Huntingtin gene (HTT), which results in the production of mutant protein (mHtt) with a toxic polyglutamine (polyQ) tract." (PMID 28194101, 2017). "Huntington’s disease (HD) is a fatal neurodegenerative disorder caused by a CAG expansion in the Huntingtin (HTT) gene." (PMID 28499347, 2017). "Huntington disease (HD) is an incurable autosomal dominant neurodegenerative disorder caused by CAG repeat expansion in exon 1 of the huntingtin (HTT) gene." (PMID 28848389, 2017). "Huntington's disease (HD) is caused by a mutation that leads to an expansion of a polyglutamine stretch in the huntingtin (HTT) protein." (PMID 28288000, 2017). "Huntington's disease (HD) is a devastating neurodegenerative disorder caused by a polyglutamine (polyQ) expansion in exon 1 of the Huntingtin (HTT) gene." (PMID 29066943, 2017). "The cause of Huntington’s disease (HD) has been identified as the abnormal expansion of a CAG repeat in exon 1 of the huntingtin gene (HTT), that is transmitted in an autosomal dominant fashion." (PMID 28099507, 2017). "One such disorder is Huntington’s Disease (HD) that is caused by a polyglutamine expansion in the human huntingtin protein (htt)." (PMID 28282438, 2017). "Huntington’s disease (HD) is caused by an unstable cytosine adenine guanine (CAG) trinucleotide repeat expansion encoding a polyglutamine tract in the huntingtin protein." (PMID 29160844, 2017). "Huntington's disease (HD) is a fatal neurodegenerative disorder, caused by a polyglutamine expansion in the huntingtin protein (HTT)." (PMID 28303108, 2017). "The discovery of the causative gene for Huntington’s disease (HD) has promoted numerous efforts to uncover cellular pathways that lower levels of mutant huntingtin protein (mHtt) and potentially forestall the appearance of HD-related neurological defects." (PMID 29256861, 2017). "Huntington’s Disease (HD) is a genetically dominant trinucleotide repeat disorder caused by CAG repeats within the Huntingtin (HTT) gene (chromosome 4p16.3) exceeding a normal range (> 36 CAGs)." (PMID 29209494, 2017). "Huntington's Disease (HD) is an autosomal dominant neurodegenerative disorder caused by a CAG expansion within the first exon of the Huntingtin (HTT) gene, which gives rise to an expanded polyglutamine tract in the huntingtin (HTT) protein." (PMID 27988204, 2017). "Huntington’s disease (HD) is an autosomal dominant neurodegenerative condition caused by an expanded CAG repeat in the gene encoding huntingtin (HTT)." (PMID 29272284, 2017). "Huntington disease (HD) is an inherited neurodegenerative disorder caused by mutations in the huntingtin gene." (PMID 28508341, 2017). "Huntington’s disease (HD) is a devastating neurological disorder caused by a dominantly inherited CAG repeat expansion in the huntingtin gene." (PMID 26819833, 2016). "Huntington’s disease is a common autosomal dominant neurodegenerative disease, which is caused by the expansion of polyglutamine repeats in huntingtin (HTT) protein, named as mutant HTT (mHTT)." (PMID 27847464, 2016). "Huntington disease (HD) is a neurological disorder caused by polyglutamine expansions in mutated Huntingtin (mHtt) proteins, rendering them prone to form inclusion bodies (IB)." (PMID 27033550, 2016). "Huntington’s disease (HD) is a neurodegenerative disease caused by a polyglutamine (polyQ) expansion in the huntingtin (HTT) protein." (PMID 26428929, 2016).
Huntington disease (continued). "Huntington’s disease is a devastating neurological disease caused by the accumulation of the polyQ-containing protein huntingtin." (PMID 27677791, 2016). "The Huntington disease (HD) is predominantly inherited, with a single gene, HTT, encoding the Huntingtin protein, at its origin." (PMID 27033550, 2016). "Monogenic disorders, such as Huntington’s disease, are identified simply through the presence, or absence, of single gene mutations; in this case a mutation in the Huntingtin protein, HTT." (PMID 27196054, 2016). "Huntington’s disease is a complex neurodegenerative disorder caused by CAG expansion in the huntingtin gene." (PMID 27390852, 2016). "Huntington's disease (HD) is caused by intracellular accumulation and aggregation of a mutant form of the huntingtin protein (mHTT)." (PMID 26941593, 2016). "Huntington’s disease (HD) is a fatal neurodegenerative disorder caused by a CAG repeat expansion in the huntingtin gene." (PMID 27170315, 2016). "When HTT gets mutated in Huntington disease, this activity of HTT also disappears and production of BDNF decreases." (PMID 27875990, 2016). "Huntington’s disease (HD) is an autosomal dominant neurodegenerative disorder caused by a CAG-repeat expansion in exon-1 of the huntingtin gene (HTT) that results in expression of a polyglutamine-expanded huntingtin protein." (PMID 27611938, 2016). "Huntington's disease (HD) is caused by a repeated trinucleotide (CAG) within the Huntingtin gene and results in choreiform movements, limb incoordination, and impaired motor function." (PMID 26997958, 2016). "In this study, we elucidated the molecular network of TRIAD and identified huntingtin (Htt), a causative gene of Huntington's disease, and two heterogeneous nuclear ribonucleoproteins (hnRNPs) involved in splicing 21 as key molecules in the network." (PMID 27124581, 2016). "Huntington's disease (HD) is a devastating neurodegenerative disorder caused by a CAG repeat expansion within exon 1 of the huntingtin gene (HTT), which encodes for an expanded polyglutamine (polyQ) tract in the huntingtin protein (HTT)." (PMID 26815359, 2016). "Mutations of the huntingtin protein (HTT) gene underlie both adult-onset and juvenile forms of Huntington’s disease (HD)." (PMID 26863614, 2016). "Huntington’s disease (HD) is an autosomal dominant neurodegenerative disorder caused by abnormal extension of a tract of CAG repeats in the first exon of the HTT gene." (PMID 26863614, 2016). "For the third one, Huntington's disease, it is caused by a polyglutamine stretch in the gene Huntingtin." (PMID 27872676, 2016). "Huntington’s disease (HD) is late-onset, progressive neurodegenerative disorder caused by expansion of polyglutamine (polyQ) repeat within Huntingtin (Htt) protein." (PMID 27506601, 2016). "These polymorphisms were in eIF4G2, a paralog of the nutrient-sensing factor eIF4G; the ceramide synthase gene schlank; and the Drosophila homolog of huntingtin, the gene underlying human Huntington’s disease." (PMID 27809764, 2016). "Mitochondria defects caused by mutant huntingtin (mtHtt) have been implicated in Huntington's disease." (PMID 27561680, 2016). "In humans, proteins such as huntingtin (Htt) with abnormally expanded polyQ regions cause neurodegenerative diseases such as Huntington’s disease (HD)." (PMID 27677791, 2016). "Huntington's disease (HD) is a fatal progressive disease linked to expansion of glutamine repeats in the huntingtin protein and characterized by the progressive loss of cognitive and motor function." (PMID 27595037, 2016). "Huntington disease (HD) is an autosomal neurodegenerative disorder caused by the expansion of Polyglutamine (polyQ) in exon 1 of the Huntingtin protein." (PMID 27713486, 2016). "Huntington’s disease (HD) is an autosomal dominant disease linked to a CAG repeat expansion in the first exon of the huntingtin gene located in chromosome 4 at position 16.3." (PMID 27653664, 2016).